CD4 (CD4 molecule)
Diseases named in the same sentence as CD4 in open-access papers (continued):
Sharing a sentence is not in itself a finding about the gene and the disease.
cancer (continued). "UCPVax is a therapeutic anti-cancer vaccine consisting of the telomerase-derived helper peptides UCP2 (TERT578–592:KSVWSKLQSIGIRQH) and UCP4 (TERT1041–1055: SLCYSILKAKNAGMS), designed to stimulate vigorous TH1 CD4 T cell responses in individuals diagnosed with cancer." (PMID 40514725, 2025). "Consequently, the decreases in CCT2 resulted in activation of CD4+ T cells and inhibition of cancer growth." (PMID 41294803, 2025). "Notably, SHROOM2 expression was associated with the infiltration of B cells, CD4+ T cells, CD8+ T cells, cancer-associated fibroblasts, macrophages, neutrophils, and mast cells in BC." (PMID 41025048, 2025). "CD4+ T cell stimulation is critical for cancer vaccine efficacy." (PMID 40543509, 2025). "One study used escalating doses of Ipi on CD4+ T cells of cancer patients." (PMID 40136348, 2025). "To validate whether our approach could be extended to other cancer sites, we conducted an MR analysis of the CD4+ T cell gene expression exposures across pan‐cancer." (PMID 41216857, 2025). "This pathway impacts CD4+ T cell function and differentiation in cancers." (PMID 40863244, 2025). "Furthermore, we found that in early‐relapse HCC, there was an increase in the proportions of CD8+ T cells, NK cells, and malignant tumor cells, while the proportions of CD4+ T cells and myeloid immune cells decreased." (PMID 40018995, 2025). "Notably, a negative correlation of MALAT1 with M1 macrophages was observed across all cancers in which it was involved, while a positive correlation with CD4+ Tcm cells was observed." (PMID 40728857, 2025). "Since both cancer growth and chronic stress can impact immune functioning in different ways, we next calculated the ratio of CD4+ to CD8+ T lymphocytes extracted from the spleens of each of the eight groups of mice." (PMID 40172096, 2025). "Moreover, the intratumoral IL-24 level correlates with cDC2 and CD4+T cell gene signatures in human cancers and better patient survival." (PMID 41009359, 2025). "Thus, our results suggest that FAM111B aids DNA repair and influences Th1/Th2 differentiation in CD4+ T cells, potentially contributing to cancer development across various types." (PMID 40243892, 2025). "In contrast, CD4+ T cell RNA-seq analysis revealed the specific expansion of cluster 2 in all 4 patients with cancer following anti–CTLA-4 and anti–PD-1 combination therapy, which corresponded to the time at which autoreactive B cells accumulated in the periphery." (PMID 41026527, 2025). "Given the range of potent effector pathways available to NeoAg-specific CD4+ T cells for the control of incipient cancers, the progressive outgrowth of primary and metastatic tumors suggests that these either do not develop or are actively suppressed under physiologic conditions." (PMID 40196575, 2025). "Subgroup analysis of TCM + ICIs vs. ICIs in cancer—CD4+T/CD8+T by different factors." (PMID 41244814, 2025). "The majority of cancer immunotherapy techniques may benefit from including CD4+ activation techniques." (PMID 40860882, 2025). "Notably, AURKA expression showed a predominantly positive correlation with activated CD4+ T cells and T helper 2 cells across cancer types." (PMID 40718709, 2025). "A subset of cytotoxic CD4+ T cells was shown to kill cancer cells in an antigen-specific manner." (PMID 41030446, 2025). "Their roles in cancer vaccines and adoptive T cell therapies are increasingly recognized, with evidence suggesting that CD4+ T cells may improve treatment outcomes." (PMID 40660400, 2025). "The reduction in lymphocytes may reflect a decrease in CD4+ T lymphocytes, leading to a weakened lymphocyte-mediated immune response to malignant tumors." (PMID 40525631, 2025). "If the antigenic peptide comes from a transformed or cancer cell, this partially activated CD4+ T cell after leaving the thymus likely will further encounter the same MHC-II-complexed antigen in the periphery, and thus its activation by this antigen will be further confirmed." (PMID 41296449, 2025).
cancer (continued). "CD4+ T cells assist other immune cells in recognizing and responding to cancer cells." (PMID 40308586, 2025). "Macrophages induce naïve CD4+ T cells to differentiate into Tregs in cancer." (PMID 40692710, 2025). "In contrast, other types of T cells that favor cancer progression and shorten survival may be present, such as regulatory T cells (such as Foxp3) and CD4 helper 2 cells." (PMID 39858287, 2025). "Devising a mechanism to activate the antitumor immune response through CD4+ Th2 cells may yield a significant therapeutic benefit in breast and other immunological cold cancers." (PMID 39782693, 2025). "The CD4+/CD8+ ratio can be used as a biomarker predicting cancer treatment response and prognosis." (PMID 40943484, 2025). "Furthermore, several studies reported that PD-L1-enriched TEVs promote cancer immune evasion by reducing the abundance of CD4 + T cells, suggesting a pivotal role of immune checkpoint protein-bearing TEVs in regulating CD4 + T cells." (PMID 40908470, 2025). "Th17 cells are a kind of CD4+ T cell that affects different cancers by mediating IL-17." (PMID 38726780, 2025). "In our previous studies, DEB-TACE had a positive antitumor performance in patients with malignant tumors, with changes in the microenvironment including increased natural killer cells and CD4+/CD8+ ratios, and decreased levels of T regulatory cells and interleukin-17A." (PMID 40771818, 2025). "However, the functional program that regulates the killing activity of cytotoxic CD4+ T cells in patients with cancer has yet to be fully elucidated." (PMID 40299576, 2025). "Given that αβ T cells are the strongest components in the immune response against tumors and are the foundation of potent cancer immunotherapies, we assessed whether PA or OA affects the proliferation and cell death of CD4 and CD8 T cells." (PMID 40603316, 2025). "Despite the decrease in the overall number of CD4+ T cells, there may also be an increased proportion of T regulatory cells among them, that was demonstrated in other types of cancer." (PMID 41228297, 2025). "For example, for patients diagnosed with human papillomavirus infection (HPV)-associated cancers, their immune systems tolerate cancer cells or are suppressed due to the disturbance of the antigen presentation process and the activation of CD8+ and CD4+ T cells." (PMID 40333256, 2025). "Additionally, NP1192 combined with anti-PD-L1blockade also significantly reduced cancer-promoting Tregs (CD4+CD25+FOXP3+), compared to the anti-PD-L1or NP1192 alone groups." (PMID 41341045, 2025). "The proportion of CD4 T cell subsets varied as cancer progressed." (PMID 41275425, 2025). "These molecules could serve as useful indicators for detecting and characterizing cytotoxic CD4+ T cells in human tissues, thereby facilitating future research and advancing therapeutic strategies that target CD4 CTLs in cancer and other diseases." (PMID 40070836, 2025). "CD4+ T cells play a crucial role in cancer immunity beyond their traditional helper functions." (PMID 40660400, 2025). "Although glutaminolysis is required for adequate T cell proliferation and cytokine secretion, the GLS1 inhibitor CB839 - which is currently approved for phase 1B clinical trials - has shown minimal effects on CD4+ T cells at higher doses than those required for growth inhibition in cancer cells." (PMID 41235226, 2025). "CIBERSORT analysis revealed that the ratio of helper T cells (CD4+) to M0 macrophages was significantly higher in Cluster 2, suggesting that CD4 memory T cells are one of the most important components of the anticancer immune response and are required for the successful elimination of cancer." (PMID 41050056, 2025). "Clinically, both senescent CD4+ T and CD8+ T cells were associated with poor survival rates and immunotherapy response in cancer patients 193-195, indicating that they may pose a barrier to effective cancer therapies." (PMID 40860134, 2025).
cancer (continued). "Neither immune defect disease nor underlying solid malignancy was associated with death, but the patients who died showed a higher proportion of haematological diseases and lower CD4+, CD8+, and B lymphocyte cell counts than the patients who survived." (PMID 39898691, 2025). "However, while these cytotoxic CD4+ T cells have also been observed in the blood of patients with cancer, the origin and functional relevance of this circulating subset and how their activity is regulated in the periphery has remained obscure." (PMID 40299576, 2025). "These cells exhibit dual functions: they not only assist B cells in germinal centers in a manner similar to CXCR5+ CD4+ T follicular helper (Tfh) cells by promoting antibody production, but they also retain cytotoxic activity, crucial in infection and cancer contexts." (PMID 40552264, 2025). "Interestingly, CD4+ Texterm phenotype exhibited the highest expression of cytotoxic markers (PRF1, GZMA, GZMB, IFNG, and GNLY), aligning with recent discoveries indicating that cytotoxic CD4+ T cells within tumors can directly kill cancer cells." (PMID 40335494, 2025). "The importance of the subset of CD4 T cells with cytotoxic capacity has been increasingly recognized, especially in the context of chronic viral infections but also in other settings like transplantation and cancer." (PMID 41376632, 2025). "CD4+ T lymphocytes play a dual role in cancer by activating cytotoxic CD8+ T cells through cytokine release, but under certain conditions, they may also impair CD8+ T cell functionality, contributing to disease progression in HBV-related HCC." (PMID 40699668, 2025). "Additionally, for both αSMA-low and αSMA-high cancers, EAO cancers had fewer CD4+ TILs/HPF than LAO cancers." (PMID 39980836, 2025). "Summary of clinical trials involving nanoparticle-based cancer targeting CD4+ T Cells." (PMID 40860882, 2025). "Although cytotoxic properties are primarily associated with CD8+ T-cells, it is important to mention a subset of CD4+ lymphocytes (cytotoxic CD4+ T-lymphocytes—CD4+ CTLs) that also possess the ability to directly kill cancer cells, albeit with MHC class II restriction." (PMID 40725022, 2025). "Effector T cells, particularly CD8+ and CD4+ subsets, play key roles in cancer dormancy." (PMID 41404065, 2025). "Furthermore, the proportion of CD8+ cytotoxic T cells decreased as the cancer relapsed (week 16), while the proportion of CD4+ T helper cells increased, along with regulatory T cells." (PMID 40701968, 2025). "The CD4/CD8 ratio is inverted early after HIV infection, and its persistence after ART has been associated with increased cancer incidence and all-cause mortality, emphasizing this specific feature of HIV-associated immunologic perturbation as impactful in antitumor responses." (PMID 40459946, 2025). "Correlation analysis of glycogen riskScore and immune cells based on 7 algorithms showed that cancer-associated fibroblast (CAF), M2 macrophage, myeloid dendritic cell, activated mast cell, monocyte, and resting memory CD4+ T cell positively correlated with the riskScore." (PMID 39895799, 2025). "We hypothesize this is because CD4+ anti-TGF-β CAR T cells lysed cancer cells, prevented exhaustion of CD8+ conventional CAR T cells, and improved the CD8+ conventional CAR T cells’ efficacy." (PMID 40107245, 2025). "ATP1A1 expression was negatively correlated with the infiltration of regulatory T cells (Tregs), follicular helper T cells, CD8+ T cells, CD4+ T cells, and memory B cells across most TCGA cancers, while it showed a positive correlation with macrophage infiltration in various cancers." (PMID 40821775, 2025). "Additionally, a pan-cancer surge in CD4+ interferon gamma (IFNG+) T follicular helper (Tfh)/Th1 cells, CD8+ Tc17 cells, and mucosal-associated invariant T cells was noted post ICB treatment." (PMID 40054456, 2025).
cancer (continued). "However, multiple studies have demonstrated that under pathological conditions such as chronic infection, cancer, and inflammation, activated CD4+ T cells can also induce the expression of NKG2A/CD94 heterodimers, particularly in Th1-skewed immune responses." (PMID 41328434, 2025). "Alongside CD8+ T cells, CD4+ T cells play a key role in anti-cancer immunity." (PMID 40136652, 2025). "Therefore, understanding the function of tissue-specific CD4+ T lymphocytes is essential in developing new strategies for treating tissue-specific diseases, as occurs in cancer." (PMID 38690280, 2024). "Ccr7+Ido1+ DCs within the immunity hubs identified in our current study not only showed expression similarity with CCR7+LAMP3+IDO1+CD274+ activated DCs or mregDCs identified in human cancers, but also showed similar spatial co-localization with CD4+ and CD8+ T cells." (PMID 39414763, 2024). "IL‐2, as reported, can boost CD4+ T cells to secrete Gzms‐B to eliminate cancer cells." (PMID 38953306, 2024). "Noninvasive in vivo imaging of the temporal dynamics of CD4+ T cells and their distribution patterns might provide novel insights into their effector and regulator cell functions during cancer immunotherapy (CIT)." (PMID 39239511, 2024). "Animal models are crucial to understanding the role of CD4 LTs in cancer pathology." (PMID 38690280, 2024). "Furthermore, during co-culture with GSDME-OE cancer cells, we noticed that T cells tended to transform into CD4+ T effector memory cells." (PMID 38169676, 2024). "By GSEA, the top enriched MSigDB gene sets in canine CD4+ PTCL (compared to control canine CD4+ T-cells) included various cancer gene signatures; miscellaneous neural cell, T cell, and NK cell gene signatures; and several cell cycle associated gene neighborhoods." (PMID 38166662, 2024). "We found that except for activated CD4 T cells and CD56dim natural killer cells, the expression level in cancer tissues was higher than that in normal tissues, and the expression level of most other immune cells was low in cancer." (PMID 39537209, 2024). "Interestingly, the co-culture of PBMCs with VSV-NDV-infected cancer cells mediated a significant upregulation of CD69 levels on human CD4+ and CD8+ T cells, while CD25 was additionally upregulated on CD8+ T cells." (PMID 39410025, 2024). "Additionally, differentiation of naïve T helper cells into Th17 CD4+ T cell is known to be tumorigenic in multiple cancer types including PDAC." (PMID 39044834, 2024). "Since all the specimens were biopsied to confirm the histopathological analysis, we could not obtain enough samples to analyze the expression of other relevant cancer immunological molecules, such as PD-L1 or CD4." (PMID 38483588, 2024). "As for other components of the TME, we found that SCD was mainly overexpressed in malignant tumor cells, endothelial cells, fibroblast cells, and macrophage cells, whereas it was relatively low for the immune cell components of CD4 Tconv cells, natural killer cells, B cells, and neutrophils." (PMID 38905386, 2024). "As a result, to evaluate CD4+ TIL in cancer tissues and determine the prognostic and biological significance of each subset, it will be necessary to assess several distinct phenotypic markers in addition to CD4+." (PMID 39712007, 2024). "The immune cells such as CD8+T cells and activated CD4 memory cells had high infiltration in cancers where higher expression levels of ITGAL indicated good prognosis, while low CD8+ T cells’ infiltration was observed in two cancer types where high ITGAL expression was linked to poor prognosis." (PMID 39605903, 2024). "CD8+ T cells can directly kill cancer cells, while CD4+ T cells usually combat cancers indirectly." (PMID 38473379, 2024). "Indeed, an increase in CD4+ T lymphocytes in BM in cancer patients has already been observed, especially in those with metastatic bone disease." (PMID 38690280, 2024).
cancer (continued). "In TNBC, cancer basal cells enriched their communication with macrophages, CD4+, and CD8+ T cells." (PMID 39483921, 2024). "However, recent evidence suggests that the overlapping T cell receptors (TCRs) of CD4+ T cells and Tregs contribute to immunosuppression and poorer cancer outcomes, specifically including inhibition of CD8+ T cell activity." (PMID 38572312, 2024). "Nevertheless, immunosuppressive signaling interactions were also elevated; for example, immunosuppressive prostaglandin E2 (PGE2), macrophage inhibitory factor (MIF), and midkine (MK) were elevated between cancer basal cells and CD4 and CD8 T cells in the older cohort." (PMID 39483921, 2024). "Additionally, positive associations were observed between XRCC1 expression and common lymphoid progenitor infiltration, as well as T cell CD4+ Th1 and Th2 cell infiltration, across various cancer types." (PMID 38217545, 2024). "We thus determined whether DRG2-depleted cancer cells with enhanced PD-L1 expression have defects in suppressing T cell activity by co-culturing mouse splenic CD4+ T cells with IFN-γ-stimulated B16F10 cells." (PMID 38802348, 2024). "Thus, the inclusion of CD4+ T cell antigens in human cancer vaccines is likely to improve their effectiveness." (PMID 39040850, 2024). "CD4+ T cell-derived EVs, in particular, may be pivotal in cancer immunotherapy as they can suppress cytokine production and effector T cell responses." (PMID 39062046, 2024). "Tregs account for 5–15% of CD4+ T cells and promote the immune tolerance of cancer cells." (PMID 39227950, 2024). "Increasing evidence emphasizes the pivotal role of CD4+ T cells in orchestrating cancer immunity." (PMID 39239511, 2024). "In other contexts (e.g., cancer, cell cycle control), p300 is a well-studied epigenetic regulator, but has not been implicated as a regulator in CD4+ T-cell exhaustion yet." (PMID 39689157, 2024). "There were significant positive correlations with T cell CD8 + cells in 23 types of cancer, with CD4 + cells in 20 types of cancer, with Neutrophil in 24 types of cancer, with Myeloid dendritic cell in 25 types of cancer, with Macrophage in 27 types of cancer, with B cell in 22 types of cancer." (PMID 39123216, 2024). "In addition, cancer cells can stimulate CD4+ T cells to secrete CCL5, inducing Fas-mediated apoptosis of CD8+ T cells." (PMID 39114657, 2024). "We investigated the association of CD4:CD8 ratio on the hazard of non-AIDS defining malignancy (NADM), AIDS-defining malignancy (ADM) and most frequent group of cancers in ART-treated people with HIV (PWH) with a CD4 and CD8 cell counts and viral load measurements at baseline." (PMID 38092042, 2024). "This may lead to further development of CD4 + Th2-cell infiltration, which promotes the development of the cancer, resulting in its poor survival rate." (PMID 37505298, 2024). "When it comes to immune responses against infections and cancer cells, CD4+ T cells are crucial." (PMID 39090094, 2024). "Thus, cancer vaccines should combine efforts to engage more active CD4+ T cell directly or indirectly." (PMID 39898278, 2024). "In addition, we showed that PIEZO1 is correlated with EMT, hypoxia, and TGF-β signaling, processes which have all been shown to be correlated with decreased CD8+ and/or CD4+ T cell infiltration in various cancer types." (PMID 38398074, 2024). "We also investigated CD4 + Tregs due to their ability to impede effective immunity against cancers." (PMID 38926643, 2024). "Furthermore, it has been observed that both CD81 and CD82 influence cytokine production in CD4 cells and affect cytotoxicity against cancer cells in CD8 cells." (PMID 38515751, 2024). "Even without encoding immunogenic cytokines (SFV-GFP replicon particles), rSFV-infected cancer cells induced strong migration of PBMC through a transwell and caused upregulation of CD4 and CD8 T cell degranulation (CD107) and differentiation (CD69) markers in cancer cell monolayers." (PMID 38425844, 2024).